ABRA (actin binding Rho activating protein)
Description:
Acts as an activator of serum response factor (SRF)-dependent transcription possibly by inducing nuclear translocation of MKL1 or MKL2 and through a mechanism requiring Rho-actin signaling.
Synonyms: STARS
Tractability: Antibody: its Gene Ontology location is reachable by antibodies, with high confidence. PROTAC: ubiquitination databases record sites on it.
Gene: Protein-coding gene on chromosome 8 (106,759,483 to 106,770,244, reverse strand). Ensembl gene ENSG00000174429.
Subcellular location: Cytoplasm, myofibril, sarcomere; Cytoplasm, cytoskeleton
Gene Ontology:
Molecular function: protein binding; actin binding
Biological process: actin cytoskeleton organization; positive regulation of Rho protein signal transduction; positive regulation of transcription by RNA polymerase II
Cellular component: plasma membrane; actin cytoskeleton; sarcomere; cytoskeleton; myofibril
Genetic constraint (gnomAD): Loss-of-function variants: 25 observed, 35.15 expected, observed/expected ratio (o/e) 0.71, 90% interval 0.52 to 0.99. The upper end of that interval is the gene's LOEUF score, 0.99, which puts it in group 4 of 6, group 1 being the genes least tolerant of losing a copy. Missense variants: 501 observed, 518.23 expected, observed/expected ratio (o/e) 0.97, 90% interval 0.9 to 1.04. Synonymous variants: 193 observed, 186.54 expected, observed/expected ratio (o/e) 1.03, 90% interval 0.92 to 1.17.
Homologues: Orthologues: chimpanzee ABRA (99% identical), macaque ABRA (97% identical), dog ABRA (85% identical), pig ABRA (84% identical), rabbit ABRA (83% identical), mouse Abra (79% identical), rat Abra (78% identical), guinea pig ABRA (71% identical), tropical clawed frog abra (52% identical), zebrafish abrab (47% identical), Drosophila melanogaster CG3630 (19% identical), Caenorhabditis elegans F36F2.1 (17% identical), and 10 more.
Diseases named in the same sentence as ABRA in open-access papers:
ABRA is named in the same sentence as 2 diseases in open-access papers, as found by Europe PMC text mining. Sharing a sentence is not in itself a finding about the gene and the disease.
ABRA shares sentences with these, for which no sentence is quoted: heart failure (1 paper); left ventricular hypertrophy (1).